FOSL1 (FOS like 1, AP-1 transcription factor subunit)
Diseases named in the same sentence as FOSL1 in open-access papers (continued):
Sharing a sentence is not in itself a finding about the gene and the disease.
tumor (continued). "FOSL1 promotes tumor recurrence and invasive growth in AM by modulating kinetochore metaphase signaling and the epithelial–mesenchymal transition pathway; thus, it represents a promising therapeutic target for AM treatment." (PMID 36185257, 2022). "Specifically, reduced expression of miRNA-4516 promoted proliferation and malignancy in TNBC by targeting FOSL1, which exerted its function as a tumor progression mediator and thus contributed to tumor development." (PMID 34790660, 2021). "Fosl1 overexpressing mice (+Dox) developed larger tumors that were more infiltrative and aggressive than controls (–Dox), which mostly grew as superficial tumor masses instead." (PMID 34399888, 2021). "Our results revealed a significant upregulation of IL17A within the tumor group when compared to the controls explaining the potential role of FOSL1 in the immune response." (PMID 33801021, 2021). "Tumorspheres were derived from –Dox and +Dox tumor-bearing mice, and Fosl1 expression was manipulated in vitro through addition or withdrawal of Dox from the culture medium." (PMID 34399888, 2021). "(H) Western blot detection of FRA-1 expression in tumorspheres derived from a Fosl1 overexpressing (+Dox) tumor." (PMID 34399888, 2021). "TBP-1 (PSMC3) depletion stabilizes FRα (FOSL1) and further increases its levels in tumor cells expressing RAS–ERK pathway oncogenes." (PMID 34503105, 2021). "In both these tumor types, we identify the FOSL1 binding motif to be highly ranked for hypomethylated/upregulated loci, indicating a possible gain of FOSL1 (significantly up ~ 3 fc, in both), in a side independent manner." (PMID 32293332, 2020). "FOSL1 belongs to the AP-1 transcription factor family and can stimulate tumor cell proliferation and metastasis." (PMID 32661324, 2020). "The decrease in the levels of Fosl1, Ccl2, and Ccl3 is expected to reduce the recruitment of cells that allow tumor cells to evade the immune surveillance, e.g., TAMs, regulatory T cells (Tregs), and myeloid-derived suppressor cells (MDSCs)." (PMID 33330473, 2020). "PI3K/Akt activation in multiple BRAF inhibitor resistant melanoma cell lines also up-regulates of FOSL1, which drives secretion of multiple factors from tumor cells that support surrounding tumor growth." (PMID 31058079, 2019). "Nuclear MYC and FOSL1 positivity in tumor cells was evaluated using a four-tiered scoring system (Section 4) and cases were classified as low (score 0–1) and high (score 2–3)." (PMID 31438567, 2019). "In our retrospective cohort, a significantly higher fraction of MYC+ and FOSL1+ tumor cells were detected in basal-type UBC compared to luminal-type." (PMID 31438567, 2019). "Injection of human mutant KRAS cells infected with the inducible FOSL1 shRNA into immunodeficient mice treated with doxycycline yielded tumours of significant smaller volume than control cells." (PMID 28220783, 2017). "Selection within the KRAS eight-gene cross-tumours signature of the candidate gene FOSL1 for follow-up studies relied on the incorporation of patient outcome information." (PMID 28220783, 2017). "Analysis of total tumour number in KP vs KPF mice showed a significant decrease in the number of tumours initiated in lung epithelial cells depleted of Fosl1." (PMID 28220783, 2017). "Collectively, these results support a functional role of the FOSL1 target AURKA in KRAS-driven tumours and unveil the dual inhibition of AURKA and MEK activation as a potential strategy to treat tumours with KRAS mutations." (PMID 28220783, 2017). "In this regard, our strategy using experimental systems that represented initial stages of KRAS-induced cell transformation and tumour progression yielded genes with a role in advanced disease such as FOSL1." (PMID 28220783, 2017). "Of note, FOSL1 expression was also found in advanced tumour lesions such as lymph node metastases (n=4)." (PMID 28220783, 2017).
tumor (continued). "Histological analysis revealed a significant decrease of tumour area in KPF compared to KP mice, despite the presence of large KPF tumours with incomplete recombination of Fosl1 floxed alleles." (PMID 28220783, 2017). "Moreover, as the important role of FOSL1 in cancer progression has been confirmed, its regulatory mechanism, which involves many tumor-related genes and signaling pathways and even noncoding genes, such as noncoding RNAs (ncRNAs), has also attracted attention." (PMID 40821785, 2025). "Interestingly, we found the MES II top marker Fosl1 to be expressed both in hypoxic and tumor peripheral zones." (PMID 41339360, 2025). "When these miRNAs are inhibited, the tumor-promoting effect of FOSL1 will naturally be restored." (PMID 40821785, 2025). "Collectively, these findings suggest that FOSL1 may play a role in tumor progression and radioresistance in GBM." (PMID 41423530, 2025). "Research has revealed that FOSL1, which is often highly expressed in tumor tissues and has an effect on malignant transformation, proliferation, invasion, anti-apoptosis and drug resistance of tumor cells, is related to tumor progression." (PMID 40821785, 2025). "Similarly, miR-4516 targeted FOSL1’s tumor-promoting activity to inhibit triple-negative breast cancer." (PMID 38694824, 2024). "FOSL1 ectopic expression was found to be increased in both CRC tissues and cells and was strongly associated with a higher risk of lymph node metastasis, advanced TNM staging, and poorer tumor differentiation." (PMID 38791400, 2024). "The depletion of FOSL1 results in a significant reduction in tumor burden, by up to 200-fold." (PMID 38791400, 2024). "Therefore, targeting FOSL1 and their downstream effectors represents a promising approach to preventing tumor recurrence and improving patient outcomes." (PMID 38791400, 2024). "Importantly, the Wnt deregulation is responsible for modulating the inflammatory response in the tumor microenvironment through the regulation of Wnt, RANKL, and FOSL1 pathways; the FOSL1 gene encodes Fos-like antigen-1 (Fra1) a direct target of IL-17." (PMID 37444389, 2023). "Moreover, knocking Fosl1 down in poorly differentiated epithelial tumor cells restores their epithelial morphology." (PMID 35163444, 2022). "In a previous study, FOSL1 was highly expressed in melanocytes, facilitating tumour growth." (PMID 35202347, 2022). "In addition, as a proto-oncogene, FOSL1 also plays a vital role in tumorigenesis and can promote tumor cell metastasis through epithelial–mesenchymal transition (EMT)." (PMID 36061185, 2022). "Moreover, the prognosis for the patients with higher FOSL1 expression can be even worse if a high FOSL1 expression coincides with elevated expression of JUN in the same tumor." (PMID 35163444, 2022). "The invasive front of the tumor discovers more intense immunohistochemical staining for FOSL1." (PMID 35163444, 2022). "Presumably, targeting FOSL1 could establish a strong barrier for the EMT tumor cells and prevent the appearance of metastases." (PMID 35163444, 2022). "In this respect, monitoring the FOSL1 level could help to define the tumor grade and choose the most efficient therapeutic strategy for individuals with advanced cancer." (PMID 35163444, 2022). "This type of tumor also shows more intensive staining for FOSL1 than respective epithelial tumors." (PMID 35163444, 2022). "FOSL1, which encodes FRA-1, is an AP-1 transcription factor (TF) with prognostic value in different epithelial tumors, where its overexpression correlates with tumor progression or worse patient survival." (PMID 34399888, 2021). "Furthermore, we found that overexpression of BRCA1 in these cells induced expression of CDH1 (encoding E-cadherin) while inhibiting expression of FOSL1 (encoding FRA1) and VIM, consistent with our finding that deficiency of Brca1 induced EMT in tumor cells." (PMID 33478572, 2021).
tumor (continued). "Besides, exosomal miR-19a-3p diminishes the content of Fos-related antigen 1 (FRA-1) which prompts the invasiveness and tumor malignancy of BC cells, by weakening the expression level of the FOS like 1 (FOSL1) gene coding for it." (PMID 33917233, 2021). "Interestingly, no change in expression levels of mesenchymal-associated genes VIM, EGFR, FOSL1 and FN1 was observed between CTCs and their primary tumours in any of the models." (PMID 34206049, 2021). "The role of FOSL1 in EMT has been studied in other tumor types." (PMID 34399888, 2021). "Moreover, the in vivo experiments confirmed that silencing AGAP2-AS1 functioned to suppress tumor growth through inhibition of FOSL1." (PMID 32199129, 2020). "Next, the ectopic expression, knockdown, and reporter assay experiments were all employed to elucidate the mechanism of AGAP2-AS1/miR-195-5p/FOSL1 in the processes of EC cell proliferation, cell cycle, apoptosis, invasion, and migration as well as tumor growth." (PMID 32199129, 2020). "In vitro studies showed that blocking the expression of FOSL1 could diminish the migration of tumor cells." (PMID 33228590, 2020). "FOSL1 inhibition significantly decreased tumour fold change compared to control shRNA." (PMID 28220783, 2017). "Accumulating evidence demonstrates that FOSL1 expression is elevated in inflamed intestinal mucosa and in IBD-associated malignancies, where it contributes to epithelial dysfunction, chronic inflammation, tumor initiation, metastasis, angiogenesis, and therapeutic resistance." (PMID 42193998, 2026). "Moreover, FOSL1 is involved in other important signaling pathways that affect tumor progression, such as the interleukin-6/signal transducer and activator of transcription 3 (IL-6/Stat3) pathway, the Wnt-β-catenin pathway, and other major carcinogenic pathways." (PMID 40821785, 2025). "Moreover, although FOSL1 may play a dual role in tumor progression, at present, research only supports the carcinogenic effect of FOSL1 in its regulation of miRNAs." (PMID 40821785, 2025). "In this review, we first provide a comprehensive overview of the expression and function of FOSL1 and ncRNAs in tumors and then focus on the mutual regulatory relationship between ncRNAs and FOSL1, as well as their regulatory effects on and mechanisms of tumor progression." (PMID 40821785, 2025). "Furthermore, particular importance is given to the function of FOSL1 in coordinating the activation of several cytokines, such as TGF-beta, and the commencement of IL-6 and VEGF production in tumor-associated macrophages (TAMs) that migrate into the tumor microenvironment." (PMID 38791400, 2024). "In addition, ARL4D, SH3RF2, and FOSL1 were found to be expressed in tumor immune cells (TICs)." (PMID 38172584, 2024). "By monitoring the levels of FOSL1, it could be possible to determine the grade of the tumor." (PMID 38791400, 2024). "One of these upregulated genes, FOSL1, encodes FRA-1, which forms a subunit of the transcription factor AP1 and plays an important role in the differentiation of osteoblasts, chondrocytes, and adipose progenitor cells in response to environmental stress and tumor formation." (PMID 36672268, 2023). "In this work, we showed for the first time that the combined inhibition of YAP and FOSL-1 mRNA expression, using siRNA-lipoplexes, induces superior control over tumor growth in vitro and in vivo, compared to the individual treatments, and a reduction of the tumor stroma." (PMID 35804874, 2022). "Therefore, high expression of FOSL1 may contribute to poor prognosis of LUAD from multiple aspects of tumor genesis and progression." (PMID 34430085, 2021). "Nonetheless, despite the central role of the mitotic machinery to mutant KRAS phenotype, the contribution of other members of the FOSL1 signature to the effect induced by FOSL1 loss remains unexplored and may also help to explain the impact of FOSL1 inhibition in homeostasis of mutant KRAS tumours." (PMID 28220783, 2017).
tumor (continued). "Furthermore, FOSL1 genetic inhibition is detrimental to both KRAS-driven tumour types." (PMID 28220783, 2017). "Finally, FOSL1 is an oncogene product with a role in tumor formation." (PMID 21143896, 2010). "Also the oncogenic transcription factor FOSL1, was downregulated in the NE tumour cell group." (PMID 18827820, 2008). "Emerging evidence indicates that FOSL1 is upregulated in GBM and facilitates tumor progression by modulating several oncogenic pathways, including MAPK, PI3K/Akt, TGF‐β, and Wnt/β‐catenin." (PMID 41556041, 2026). "Functionally, genetic depletion of FOSL1 or pharmacological inhibition of SMARCA4 reduced cell proliferation and migration and suppressed tumor growth in vitro and in vivo." (PMID 42010258, 2026). "In the case of SED, 225 TFs were analyzed, with TFBSs of 10 TFs identified as enriched in tumor-specific domains (T-SED), including TP63, SMAD3, JUND, and FOSL1/2." (PMID 41323280, 2025). "In contrast, the ED analysis revealed 204 TFs, with 30 showing substantial tumor-specific TFBS enrichment, including TP63, FOSL1, JUND, JUNB, and KLF5, underscoring their potential roles in tumorigenesis." (PMID 41323280, 2025). "We identified tumor-specific super-enhancer domains (T-SEDs) enriched for key TFs, including TP63, FOSL1, and JUND, and demonstrated that these domains regulate genes critical to oncogenic signaling and proliferation." (PMID 41323280, 2025). "The AP-1 complex consists of Jun family members (JUNB, c-JUN, JUND and v-JUN) and Fos family members (FOS, FOSB, FOSL1 and FOSL2), which directly promotes PD-L1 expression in tumor cells." (PMID 40599804, 2025). "We mapped H3K27ac-marked super-enhancers (SEs) via ChIP-seq in HPV+ patient-derived xenografts (PDXs) and normal oropharyngeal mucosa, identifying tumor-specific SE domains (T-SEDs) enriched for transcription factors (TFs) including TP63, FOSL1, and JUND." (PMID 41323280, 2025). "Among them, Fos-like antigen 1 (FOSL1) has gained attention for its prognostic significance across multiple cancers, where its elevated expression correlates with tumor progression and poor patient survival." (PMID 41423530, 2025). "Several tumor-specific TFs were detected within the ED and SED, including TP63, FOSL1, JUND, GRHL2, SNAI2, KLF5, TP73, and SMAD3." (PMID 41323280, 2025). "POSTN activates the PI3K/AKT/β-catenin/FOSL1 pathway in an autocrine manner to promote GSC self-renewal and tumor growth." (PMID 39227950, 2024). "Our findings revealed that the TFs E2F1, HMGA1, MYC, FOSL1 and CREB3 exhibited exceptional levels of activity within C2 UBE2C+ tumour cells." (PMID 38894657, 2024). "It would likely be more effective to target specific LTR10 enhancers that contribute to tumor phenotypes or target the transcriptional activators of LTR10 elements instead (e.g., FOSL1)." (PMID 39018396, 2024). "According to human data derived from the TCGA and GTEx databases, decreased expressions of miR-4516 and increased expressions of Wnt 8B, DVL3, FOSL1, CCNA1, CCNB1, CDK1, and CDK2 in tumor tissue contributed to the progression of LUAD." (PMID 38930863, 2024). "FOSL1 or FOS Like 1, AP-1 Transcription Factor Subunit is a leucine zipper protein that regulates tumor cell proliferation and survival in cancer." (PMID 38172584, 2024). "The expressions of miR-4516 were lower, while the expressions of Wnt 8B, DVL3, FOSL1, CDK1, CDK2, CCNA1, and CCNB1 were enhanced in tumor tissue compared to normal lung tissue in the human samples." (PMID 38930863, 2024). "Taken together, the interaction between HOXA11-AS1, FOSL1, PTBP1, and PD-L1 forms a crucial axis that collectively enhances proliferation, metastasis, immune escape, and tumor growth." (PMID 38791400, 2024).
tumor (continued). "Fluorescent images of the whole lungs and quantified tumor area suggested that high expression of PRSS3 and FOSL1 resulted in larger primary lung tumors, but elevated PAR2 levels did not have similar effects." (PMID 37395651, 2023). "In a cohort of 15 desmoplastic fibroblastomas, we found strong FOSL1 immunopositivity in 12/15 cases (including one recurrent tumour DF10), 10 of which harboured FOSL1 rearrangements at the transcript level." (PMID 36426824, 2023). "Among the top 10 significantly correlated TFs with A3A RNA levels in bulk RNA-seq profiles, three TFs' (FOSL1, NFKB1 and VEZF1) expression levels were greatly different between tumor and normal tissues." (PMID 37215984, 2023). "Our results suggested that FOSL1, CEBPD, MXI1 and YY1 were critical TFs of tumor invasion induced by hypoxia, and they can be used as an independent prognostic signature to predict GBM survival." (PMID 37441593, 2023). "We further demonstrate that rearrangements in FOSL1 and, less commonly FOS represent a recurrent and specific feature in the majority of these tumours." (PMID 36426824, 2023). "Mice tumor models revealed the effectiveness of Axitinib and Entinostat, two small molecule inhibitors targeting CEBPD and FOSL1 against tumors." (PMID 37441593, 2023). "The peri-tumoral injection of lipoplexes lead to a significant decrease in the tumor growth in both Athymic Nude-Foxn1nu and C57BL/6 mice, mainly in those receiving the combination of four siRNAs, targeting both YAP and FOSL-1." (PMID 35804874, 2022). "Among the downregulated genes were several known to activate proliferation of tumor cells (NOTCH1, HMGA2, PTK2, FOSL1, GREM1 and EGR1)." (PMID 35885035, 2022). "Dimers of FOS (c‐FOS, FOS‐B, FRA‐1/FOSL1 and FRA‐2/FOSL2) and JUN (c‐JUN, JUN‐B, and JUN‐D) build the AP1 complex, which can drive tumor progression and treatment resistance." (PMID 35604882, 2022). "In this work, we propose the use of small interfering RNA (siRNA) to inhibit the combined expression of FOSL-1 and YAP, two signaling proteins related with tumor cell proliferation and survival." (PMID 35804874, 2022). "In this study, we showed that FOSL1, a target gene of MAPK signaling, was expressed in the nuclei of AM cells and correlated with local tumor invasion and recurrence." (PMID 36185257, 2022). "Here, we provide evidence that manipulation of NF1 expression levels in patient-derived BTSCs has a direct consequence on the tumor-intrinsic MGS activation and that such activation can at least in part be mediated by the modulation of FOSL1." (PMID 34399888, 2021). "In contrast, the reduced tumor volume and weight induced by AGAP2-AS1 silencing was counteracted following overexpression of FOSL1." (PMID 32199129, 2020). "Accordingly, by using double sequential immunostaining, a significant fraction of STAT3+ tumor cells in a set of basal-type MIBC co-expressed MYC and FOSL1." (PMID 31438567, 2019). "Tumor status induced a significant decrease in the expression of FIGF (P < 0.0001), ADIPOQ (P < 0.0001), LEP (P = 0.0009), PTHLH (P = 0.0345) and FOS-like Antigen 1 (FOSL1; P < 0.0001) compared with expression in corresponding non-tumor tissue." (PMID 27857161, 2016). "Then, we compared the mRNA levels of several TGF-β-related EMT-regulators including SNAI1, SNAI2, HMGA2, FOSL1, SP1, ZEB1, ZEB2 (SIP1), and TWIST1 in primary tumor tissues of MDA-MB-231-xenografted mice." (PMID 26462028, 2015). "Another example of miRNA regulatory module consisting of the proto-oncogene FOS-like antigen-1 (FOSL1) and the candidate tumor suppressor miR-138 has been recently reported." (PMID 23271365, 2012). "Additionally, we found that FOSL1 promotes stemness in GBM cells, thereby enhancing the survival of a subpopulation of stem‐like tumor cells known to exhibit greater resistance to standard therapies, including TMZ." (PMID 41556041, 2026).